CXCL13 (C-X-C motif chemokine ligand 13)
Diseases named in the same sentence as CXCL13 in open-access papers (continued):
Sharing a sentence is not in itself a finding about the gene and the disease.
tumor (continued). "One study found that CXCL13 released by M2 polarization of macrophages activates the CXCL13/CXCR5 axis in tumor cells and promotes CRC liver metastasis." (PMID 35935996, 2022). "In the context of malignancies, the CXCR5/CXCL13 axis induces proliferation, growth, invasion and migration of malignant cells and correlates with poorer prognosis, more metastasis, and larger tumor size in many cancers." (PMID 36221115, 2022). "The chemokine CXCL13 and its receptor have important roles in angiogenesis and tumor cell migration, invasion, and metastasis." (PMID 36199786, 2022). "The levels of six cytokines differed among groups, including significant elevations in aged DIO mice, relative to the other groups, in the tumor-promoting chemokines CXCL13, CCL7, and CCL11." (PMID 36686775, 2022). "Cancer-associated fibroblasts secrete CXCL13 to recruit CXCR5+ B cells expressing lymphotoxin-α1β2, which expands TLSs in the tumor microenvironment." (PMID 35053457, 2022). "CXCL13 is a key molecular determinant of the formation of prognostically favorable TLSs and is considered to be a surrogate marker for tumor TLS." (PMID 36341460, 2022). "CXCL13 expression recruits additional immune cells to infiltrate the tumor environment to attack cancer cells following immunotherapy treatment." (PMID 35053457, 2022). "The expression of cytokines, such as CXCL9, CXCL10, CXCL11 and CXCL13, that attract specific immune cells at the tumor site was significantly higher in HBV and HCV tumors than in non-B, non-C tumors." (PMID 36557005, 2022). "Of note, CXCL13 through IL-10 induction promotes tumor macrophages in tissues that tend to develop in M2c type." (PMID 35570844, 2022). "Production of IL-21, CXCL13, and infiltration by cytolytic CD4 and CD8 T cell infiltrates associate with IMAE development in tumor models and human plasma." (PMID 36314014, 2022). "On the other hand, the suppression of IFN signaling in tumor cells stimulates the production of chemokines, such as CXCL13, which results in tumor infiltration of NK cells and subsequent inhibition of tumor progression." (PMID 36458816, 2022). "While CXCL1 and CXCL10 levels significantly decreased after tumor resection, postoperative CXCL13 levels were significantly higher compared to preoperative values." (PMID 36077611, 2022). "Like Tregs, B cells also generate regulatory B cells (Bregs) through their own activation and release chemokine CXCL13 to infiltrate the microenvironment, which is both tumor-promoting and tumor-suppressive." (PMID 35965504, 2022). "In another study, the exploratory analysis identified distinct gene signatures associated with tumor response and resistance to anti-PD-1 monotherapy in HCC patients also showed that CXCL13 was positively correlated with a better response to anti-PD-1 therapy." (PMID 35053457, 2022). "Production of CXCL13 within the tumor milieu is proposed to impact proliferation, migration, and invasive properties of cancer cells." (PMID 35392977, 2022). "A potential clinical implication of circulating CXCL13 as a novel biomarker for patient stratification before tumor resection should be considered with caution." (PMID 36077611, 2022). "High levels of CXCL13 expression resulted in increased lymphocytes infiltration in the tumor, as assessed by immunofluorescence." (PMID 35053457, 2022). "CXCL13 is an important factor involved in the recruitment of immune cells to the tumor microenvironment and serves as a key molecular determinant during the formation of tertiary lymphoid structures." (PMID 36430217, 2022). "CXCL13-producing CD4+ T cells induced by tumor environments such as TGF-β are important for the initial formation of TLS." (PMID 35552285, 2022). "On the other hand, CXCL13 was also reported to be fully capable of attracting anti-tumor immune cells to TME and correlated with favorable prognosis." (PMID 36685946, 2022).
tumor (continued). "In metastatic CRC, tumor-expressed miR-934 led to increased production of CXCL13 in M2-like TAMs and activated a CXCL13/CXCR5/NFkB/p65/miR-934 positive feedback loop in cancer cells." (PMID 36248881, 2022). "Here, the Kaplan–Meier curve analysis revealed significantly impaired OS in BTC patients who showed strongly increasing CXCL13 levels (>29.07 pg/mL) after tumor resection compared to patients with decreasing or only mildly increasing CXCL13 levels." (PMID 36077611, 2022). "Mice with 4T1 tumours also had a subtler increase in CXCL13 relative to normal levels, and a subtle increase in IL-6 and a subtle decrease in CXCL1 compared to CT26-bearing animals." (PMID 35226704, 2022). "We summarize the previous findings examining the association between CXCL13/CXCR5 expression and the clinical response to tumor immunotherapy." (PMID 35053457, 2022). "CXCL13 in the tumor microenvironment of many different types of cancer, and CXCL13 is associated with favorable outcomes in cancer patients treated with ICIs." (PMID 36013407, 2022). "Together, these data suggest that future studies should also concentrate on later time-points after tumor resection to fully illuminate the kinetics of circulating CXCL13 after tumor resection." (PMID 36077611, 2022). "Increasing research has reported the detection of CXCL13 in the tumor microenvironment of many different types of cancer." (PMID 35053457, 2022). "In TCGA bulk transcriptomes, we quantified the expression of two T cell programs of anti-tumor reactivity and effector function (‘CXCL13 T cell’ and ‘Cytotoxicity’ programs) that this study had identified as differentially active between MSI-H and MSS CRCs." (PMID 35773407, 2022). "In control, autocrine chemokine ligand 13 (CXCL13)-C-X-C chemokine receptor type 5 (CXCR5) axis promoted tumor development and progression in HCC and TNBC." (PMID 35392977, 2022). "CD4+ Tregs and CD4+/CXCL13+ T cells were predominantly identified in tumour tissues, demonstrating that malignant cells are the key elements that induced immune‐tolerance." (PMID 36305631, 2022). "Currently, CXCL13 has been found overexpressed in malignant tissues and coordinates tumor progression by modulating cell-cell interactions and lymphocyte recruitment in the TME." (PMID 35570844, 2022). "There is also evidence that CXCL13 secreted by PD‐1 high expressing tumor infiltrating CD8+ lymphocytes helps to induce other immune cell subsets into TME, including B lymphocytes and T follicular helper cells (TFH cells)." (PMID 35702353, 2022). "Naïve CD4+ T cells differentiate into T helper 1 (Th1)-oriented TFH cells that produce CXCL13 in tumor microenvironments after being primed by antigen-presenting cells in the lymph node." (PMID 35053457, 2022). "Altogether, our findings suggest that bidirectional interactions of MΦ with MM tumor cells result in M2 MΦ polarization, CXCL13 induction, and subsequent OC activation, enhancing their ability to support bone resorption and MM progression." (PMID 36217194, 2022). "CXCL13 plays an important role in shaping the anti-tumor microenvironment by facilitating immune cell recruitment, their activation and regulating the adaptive immune response." (PMID 36341460, 2022). "Paradoxically, CXCL13 has been shown to drive several pro-growth and invasive signaling pathways across multiple tumor types, showing that the CXCL13-B cell axis plays a double role in anti-tumor immunity." (PMID 36497450, 2022). "Tumors express CXCR5 and produce its ligand, CXCL13, to recruit B cells and T cells into tumor microenvironments where tertiary lymphoid structures, resembling germinal centers, are developed and antibody production occurs." (PMID 36314014, 2022). "The CXCL13 signature and the 12-chemokine signature were also significantly enriched in neoadjuvant tumor lesions, indicating increased lymphocytes infiltration and TLS formation after neoadjuvant chemoimmunotherapy." (PMID 35831283, 2022).
tumor (continued). "At the moment, various novel approaches are being employed to inhibit CXCL13/CXCR5 signaling in the tumor microenvironment and our study is in line and further support this effort by providing additional valuable information." (PMID 36217194, 2022). "The TLS-related molecule CXCL13 is associated with good prognosis in HCC patients, and the expression of CCL19 and CCL21 in tumours can promote the anti-tumour effect of TILs." (PMID 36291944, 2022). "B cell infiltration and CXCL13 expression in the tumor area have a relationship with accelerated tumor growth and developed metastasis." (PMID 35563678, 2022). "On the other hand, cancer cells secrete CXCL13 to immune cells, which are capable of production of cytokines directly promoting tumor progression and linking immune suppression." (PMID 35570844, 2022). "CXCL13 also influence tumor development and prognosis, and be a potential target for cancer treatment." (PMID 35141160, 2022). "Among them, VSIG4, SIGLEC1, and CXCL13 were significantly positively correlated with estimate scores, stromal scores, and immune scores in pan-cancer, while negatively correlated with tumor purity." (PMID 36544770, 2022). "We next compared the circulating levels of CXCL1, CXCL10 and CXCL13 between BTC patients with different tumor and clinical characteristics." (PMID 36077611, 2022). "A further intriguing aspect of CXCL13 biology is that it acts as a chemoattractant for B cells, which were also identified as an important feature of 4T1 tumour growth in our analysis." (PMID 35226704, 2022). "Genes characterising GPR56+CD161+CXCL13+ Tregs were also mirrored in other T‐cell subsets in both the tumor and the autoimmune setting." (PMID 36204213, 2022). "Another study identified a new subset of CD4+ Th-CXCL13 with tumor-resident gene characteristics in NPC." (PMID 35663939, 2022). "CXCR5 is the receptor for CXCL13, which is secreted at the tumor site to recruit B cells from circulation." (PMID 36012390, 2022). "We have also reported that tumor-reactive CD8+ T cells produce CXCL13, and the frequency of those cells among the DP CD8+ cells positively correlated with the frequency of CXCL13+ DP CD4+ cells in both HNSCC and CRC." (PMID 35439168, 2022). "Expression of both CXCL13 and CD79A has been linked to TLS, which in turn is predictive of tumor response to immunotherapy and favorable outcome in many tumor types, including MIBC27–30." (PMID 35027623, 2022). "In penile cancer, enforced expression of CXCL13 stimulates tumor metastasis by inducing the expression of metastasis-related MMP2/MMP9 through STAT3 and ERK1/2 signaling pathways." (PMID 36612163, 2022). "It is rather unlikely that physicians and/or BTC patients would decide against a potentially curative tumor resection if it were technically feasible based on a preoperative CXCL13 elevation above the prognostic cut-off value." (PMID 36077611, 2022). "The Tfh cell subset capable of secreting CXCL13 converts Treg-mediated immunosuppression into adaptive anti-tumor immune activity." (PMID 34922542, 2021). "We demonstrate that IL-33 catered by Cxcl13-Cre+ FSCs to tumor-infiltrating CD8+ T cells reduces local T cell exhaustion and thereby sustains control of tumor growth." (PMID 34354077, 2021). "CXCL13 signaling is involved in multiple diseases and exhibits context-dependent effects in inflammatory conditions and tumor tissues." (PMID 34947813, 2021). "On a per-patient basis, tumor cell-resolved CXCL13 expression increased in 100% of responders post- vs pretreatment versus 29% of nonresponders." (PMID 34795254, 2021). "In this experiment, we also added the AKT inhibitor A3149 to further evaluate the mechanism of CXCL13 in promoting tumor proliferation and EMT." (PMID 34922542, 2021). "Among them, CXCL9 is crucial for recruiting immune T cells into the TME35, XCL2 plays a role in recruitment of DCs36, and CXCL13 can recruit both T cells and B cells into tumor tissues to enhance tumor immunity." (PMID 34556668, 2021).
tumor (continued). "We found that the protein expression CXCL9 (p = 0.012), CXCL10 (p = 0.003), CXCL11 (p = 0.011), CXCL13 (p = 0.004) were higher in tumor tissues than that in adjacent tissues." (PMID 34321012, 2021). "Our results indicated that the CXCL13 expressed in the 4T1 tumor microenvironment mediated a systemic antitumor immune response." (PMID 35693216, 2021). "Then, we screened possible factors associated with poor outcomes, including having tumours, a chronic onset and factors associated with relapses, which included having lower levels of CSF BAFF and a larger ratio of serum TGFβ1/serum CXCL13." (PMID 34872566, 2021). "Knockdown of CXCL-13 resulted in re-sensitization of tumor cells with a significant increase in the number of B-cell infiltrating into the tumor cells." (PMID 34571731, 2021). "Further, the TIMP1 and CXCL13 proteins were significantly related to the tumor immune infiltration of CD8+ T cells." (PMID 33579281, 2021). "The results showed that the expression of CXCL1-2 and CXCL12 decreased with the development of tumor, while CXCL13 was opposite." (PMID 34123826, 2021). "In particular, PD-1hiCD39+ CD4 TILs expressed the exhaustion transcription factor TOX and the chemokine CXCL13 and were tumor antigen specific." (PMID 33332284, 2021). "Further investigations showed that CXCL13 expression in the 4T1 tumor microenvironment elicited long-term antitumor immune memory, and rejection of distal parental tumor." (PMID 35693216, 2021). "In this study, we found that M2 macrophages in the tumor tissue microenvironment produce high levels of CXCL13 and that by attaching to the CXCR5 receptor on tumor cells, they promote the proliferation, migration, invasion, and EMT." (PMID 34922542, 2021). "In parallel to these functions, CXCL13 plays a key role in promoting immune infiltration in the tumor via binding to CXCR5 and controlling tumor behavior by binding to receptors on the tumor surface." (PMID 34445452, 2021). "These PD-1T tumor-infiltrating lymphocytes play an active role in the recruitment of immune subsets to the TME via the secretion of CXCL13 and show predictive potential for response to PD-1 blockades." (PMID 34947813, 2021). "CCR5 binds many ligands which are overexpressed in the tumor microenvironment including CXCL13 (BCA-1), CCL3 (MIP1α), CCL3L1, CCL4 (MP-1β), CCL8 (MCP2), CCL11 (eotaxin), CCL13 (MCP-4), and CCL16 (HCC-4)." (PMID 33485378, 2021). "All cells with a CXCL13 log1p normalized read count >0.5 were analyzed and tumor cells had the highest mean expression of CXCL13." (PMID 34795254, 2021). "Next, CXCL13-mediated immune cell infiltration in 4T1 tumor microenvironment was analyzed by flow cytometry." (PMID 35693216, 2021). "Caki-1 cells were placed under the skin of nude mice to detect the tumor-promoting effect of the chemokine CXCL13 in vivo." (PMID 34922542, 2021). "The in vivo mouse CXCL13 expression was confirmed by immunohistochemical staining of frozen tumor tissue sections." (PMID 35693216, 2021). "CXCL9 (p = 0.027), CXCL10 (p < 0.001), CXCL11 (p = 0.002) and CXCL13 (p < 0.001) were significantly up-regulated in tumor tissues compared with tumor-adjacent tissues, while the expression of CXCL12 (p = 0.149) was down-regulated." (PMID 34321012, 2021). "Although the promoter of the CXCL13 gene contains HRE, no data are available on the direct chronic hypoxia-induced upregulation of CXCL13 in a tumor cell." (PMID 33467722, 2021). "The increased expression of six CXC chemokines (CXCL4, CXCL9, CXCL10, CXCL11, CXCL12, and CXCL13) was related to tumor progression." (PMID 33767987, 2021). "Ablation of Il33 gene expression in Cxcl13-Cre-positive FSCs reduces the functionality of intratumoral T cells and unleashes tumor growth." (PMID 34354077, 2021).
tumor (continued). "We further examined the expression of known tumor-promoting markers in these immune subpopulations, confirming that CD4_CXCL13, CD4_FOXP3, CD8_CXCL13, CD8_ISG15, Mac_C1QA, Mac_ISG15 and Mac_SPP1 cells were tumor-promoting immune cells." (PMID 35087839, 2021). "This confirmed that higher expression of several known CTCL marker genes, including CD27, IL-32, CXCL13, BATF, and TIGIT28–32, was associated with spots with higher frequencies of tumor cells (see yellow highlighted genes)." (PMID 34795254, 2021). "The levels of CXCL13 and IL-21 expressed by tumor-infiltrating Tfh cells in patients who received neoadjuvant chemotherapy was higher than those in patients who had not, although the proportion of Tfh cells showed no obvious difference." (PMID 34359579, 2021). "In the same study, CXCL13 exhibited the most marked selective expressions in ICI responders across 1008 patients receiving ICI for different tumor types." (PMID 34572771, 2021). "Treatment with recombinant CXCL13, IL-21 and Tfh cells alleviated tumor growth and enhanced the infiltration of CD8+ T cells and B cells, as well as B cell maturation in a PDAC mouse model." (PMID 34359579, 2021). "Tfh cells promoted the formation of an immunoactive tumor microenvironment by secreting CXCL13 and IL-21, and the high infiltration of Tfh cells correlated with better patient prognosis." (PMID 34359579, 2021). "It is discovered that the original Tfh cells in BRCA secrete CXCL13 to promote the accumulation of Tregs in the tumor, inhibit the body’s anti-tumor immunity, and ultimately promote the development of BRCA." (PMID 33936088, 2021). "CXCL13 enhances cancer metastasis signaling in an autocrine or paracrine manner, since it is secreted by tumor cells or other cell types, such as stromal cells and lymphocytes." (PMID 34947813, 2021). "Microscopic analysis of B16F10 tumors growing in Cxcl13-Cre/tdTomato EYFP mice revealed that lineage-traced EYFP+ cells localized mainly in the tumor margin co-express PDPN both in PBS- and artLCMV-treated tumors (arrowheads)." (PMID 34354077, 2021). "To find new potential checkpoints, we investigated the cell-cell communications between tumor-promoting immune cells (CD4_CXCL13, CD4_FOXP3, CD8_CXCL13, CD8_ISG15, Mac_C1QA, Mac_ISG15, Mac_SPP1 and cDC3_LAMP3) and the ductal epithelial cells." (PMID 35087839, 2021). "At the moment, various novel approaches are being employed to inhibit CXCL13/CXCR5 signaling in the tumor microenvironment." (PMID 34922542, 2021). "Instead, we explored the method of intravenous injection of CXCL13 into one of the experimental groups of mice to intervene in tumor growth." (PMID 34359579, 2021). "It is well established that CXCR5 and its ligand CXCL13 play important roles in inflammation and immunity, and recent studies raised roles for this receptor in growth and metastasis of tumor." (PMID 34294713, 2021). "CXCL13 and IL1B are both implicated in both cancer metastasis and recruitment of immune cell populations to tumor cells, particularly B cells and macrophages." (PMID 33888854, 2021). "Further investigations showed that CXCL13 mediated long-term antitumor immune memory and rejection of distal parental tumor." (PMID 35693216, 2021). "Apart from the recruitment of tumor-infiltrating B cells, CXCL13, expressed by interleukin-6 (IL-6)-treated human bone marrow endothelial (HBME) cells, mediates PC-cell invasion, adhesion to HBME cells, and αvβ3-integrin clustering." (PMID 34947813, 2021). "In responders, pembrolizumab therapy appears to promote T cell activation and upregulate CXCL13 in tumor cells." (PMID 34795254, 2021). "By analyzing the TCGA and GEO database and applying ESTIMATE algorithm and a series of bioinformatic methods, we obtained tumor microenvironment associated genes (CD79A, CXCL13, IL6 and CCL19), which were related to the clinical outcome of PRCC patients." (PMID 33993869, 2021).